CTLA4 (cytotoxic T-lymphocyte associated protein 4)
Diseases named in the same sentence as CTLA4 in open-access papers (continued):
Sharing a sentence is not in itself a finding about the gene and the disease.
melanoma (continued). "In mouse models of melanoma and colon cancer, anti-PD-1 treatment induced the expansion of tumor Tregs with a follicular phenotype (Follicular regulatory T cells or Tfr, Foxp3+ Bcl6+), and Tfr depletion by pretreatment with anti-CTLA4 improved tumor control." (PMID 35874810, 2022). "In 2011, the United States Food and Drug Administration (FDA) approved the anti–CTLA-4 antibody ipilimumab for patients with stage IV melanoma, followed by the anti–programmed cell death 1 (anti–PD-1) antibodies nivolumab and pembrolizumab in 2014 for the second and subsequent line treatment." (PMID 36006646, 2022). "Firstly, they were used in the treatment of advanced melanoma, e.g., CTLA-4 and PD-1 blockers." (PMID 35267512, 2022). "HRR may serve as an independent predictor of anti-CTLA-4 therapy efficacy in patients with advanced melanoma and their clinical value warrants further investigation." (PMID 35990677, 2022). "Kaplan–Meier survival analysis showed that IEVscore stratified melanoma patients (Vanallen cohort) into two groups with different prognoses, with patients having high-IEVscores showing poorer clinical outcomes and greater resistance to anti-CTLA4 therapy." (PMID 36096781, 2022). "Combinatorial therapy of anti-CTLA-4 and anti-PD-L1 blockade displayed more evident tumor regression in approximately 50% of patients with advanced melanoma, in some cases, more than 80% of total patients were presented with disease remission and long-term free survival." (PMID 35252014, 2022). "While phase I/II clinical trials in melanoma patients testing DNMTi’s in combination with anti-CTLA-4 or anti-PD-1 mAbs are still ongoing, a phase II trial in acute myeloid leukemia reported on the combination of the DNMTi Azacitidine and PD-1 inhibitor Nivolumab." (PMID 35634329, 2022). "In a poorly immunogenic melanoma mouse tumor model, combinatorial treatment with granulocyte-macrophage colony stimulating factor (GM-CSF)–transduced tumor cell vaccine and anti-CTLA-4 resulted in tumor rejection that was directly correlated with increased Teff/Treg ratio." (PMID 36159809, 2022). "To determine if the bispecific antibodies that target CHI3L1 and CTLA-4 particularly effective, we generated bispecific antibodies and their antitumor effects in a T cell-melanoma cell coculture system were evaluated and compared to individual antibodies, alone or in combination." (PMID 36618349, 2022). "Recently, Lozano and collaborators demonstrated that in melanoma patients treated with anti-PD-1 or anti-PD-1 and anti-CTLA-4 combination, two pretreatment factors in peripheral blood - activated CD4 memory T cell abundance and TCR diversity - were associated with severe irAEs development." (PMID 35432346, 2022). "In our current analyses, we found that pyroptosis is significantly associated with the increased expression of multiple immune checkpoint factors in the melanoma microenvironment, such as PD-1/PD-L1, CTLA4, TIM3, LAG3, and immune activation-related molecules, including OX-40, CD40, and CD86." (PMID 36513682, 2022). "In patients with melanoma, the combination of radiotherapy and CTLA-4 can induce abscopal effects." (PMID 36119033, 2022). "Inhibitors of PD-1, PD-L1 and cytotoxic T-lymphocyte-associated protein 4 (CTLA-4) are currently and successfully used in the treatment of non-small-cell lung cancer, advanced melanoma, and Hodgkin’s lymphoma, among others." (PMID 35159017, 2022). "In several tumors, such as melanoma, the expression levels of TIGIT in CD8+ T cells are upregulated, and the high TIGIT/DNAM1 ratio in Tregs is associated with poor prognosis following PD-1 and/or CTLA4 pathway blockade." (PMID 35037899, 2022). "Currently, CTLA-4 inhibitor Ipilimumab has been approved by FDA for the adjuvant treatment of stage III melanoma and the treatment of advanced melanoma, and clinical studies of Ipilimumab and Telimomab in kidney cancer, prostate cancer and lung cancer have been widely carried out." (PMID 35590394, 2022).
melanoma (continued). "Recent therapies that reverse this evasion, specifically via the inhibition of PD-1 and CTLA-4, termed “immune checkpoint blockade,” have shown durable responses for a portion of patients with solid tumors and are especially effective in melanoma and non–small cell lung cancer." (PMID 35838045, 2022). "Like cholesterol and obesity, this may relate to rates of intratumoural CD8+ T‐cell exhaustion, with an analysis of pre‐treatment melanoma samples finding those from men exhibiting higher CD8+ TIL fractions strongly positive for CTLA4 and PD1." (PMID 35394069, 2022). "Combined therapeutic strategies from preclinical and clinical studies have shown that anti-PD-1 plus anti-CTLA-4 (nivolumab and ipilimumab) treatments elicit stronger immune stimulation in stage IV melanoma than monotherapy alone, resulting in a favorable anti-tumor immune response." (PMID 36613491, 2022). "In order to study the differences in immunotherapy and chemotherapy of different immune molecular subtypes, we used the method of subclass mapping to compare the three metabolic subtypes with the GSE91061 dataset (melanoma receiving anti-PD-1 and anti-CTLA-4 treatment)." (PMID 35875026, 2022). "Immune checkpoint inhibitors (ICIs), namely programmed cell death 1 (PD-1) or cytotoxic t-lymphocyte antigen 4 (CTLA-4) inhibitors, are currently the standard of care for the treatment of advanced melanoma, with robust and durable responses in a subset of patients." (PMID 36428582, 2022). "Similarly, combined use of GM-CSF cell-based vaccines (GVAX) and CTLA-4 inhibitor decreased tumor size and restored the antitumor immune responses in melanoma, prostate, and also PDA murine model." (PMID 34980128, 2022). "Interestingly, DNMT inhibitors sensitized a pre-clinical melanoma model to CTLA-4 immunotherapy by de-repressing endogenous retroviruses (ERVs) and activating an IFN response." (PMID 36497341, 2022). "Interestingly, co-treatment of an MMP-2/-9 inhibitor and PD-1 or CTLA-4 blockade enhanced the therapeutic efficacy in the treatment of mouse models of melanoma and lung cancer." (PMID 35558554, 2022). "Thus, blocking the different immune checkpoints has become a cornerstone of modern immunotherapy and the usefulness of CTLA-4, PD-1 and PD-L1/2 blockers in advanced melanoma therapy has been most widely studied to date." (PMID 35719931, 2022). "On top of the success of anti-CTLA-4 antibody, ipilimumab, and antibodies against PD-1 and PD-L1, trials combining both ipilimumab and nivolumab demonstrated encouraging results in advanced melanoma." (PMID 36341387, 2022). "Moreover, CD8+ T cells were also suggested to be a good predictor of the response to anti CTLA4 molecules in melanoma patients." (PMID 35207516, 2022). "Such hypothesis is also supported by Gilley and Dube who successfully combined anti-CTLA4 or anti-PD-L1 blockade with Listeria expressing Ova in melanoma." (PMID 35173308, 2022). "Indeed, the combination of IDO1 inhibitor with CTLA-4 and PD-1/L1 antibodies demonstrated synergistic antitumor activity in glioma and melanoma mice models." (PMID 35173722, 2022). "When facing triple wild-type melanoma, the only therapy option available is immunotherapy, represented by anti-programmed cell death protein 1 (PD-1) and/or anti-cytotoxic T cell antigen 4 (CTLA-4) antibodies." (PMID 36012593, 2022). "A CTLA4 super-agonist (ipilimumab) has been approved to treat melanoma." (PMID 36271469, 2022). "Likewise, the higher expression levels of the IFN-γ-responsive genes appears to be vital for the clinical success of anti–CTLA-4 mAb as evidenced by the analysis of tumor specimens from melanoma patients treated with ipilimumab." (PMID 35433680, 2022). "Melanoma-intrinsic activated β-catenin pathway, the product of the catenin beta 1 (CTNNB1) gene, has been associated with low/absent tumor-infiltrating lymphocytes, accelerated tumor growth, metastases development, and resistance to anti-PD-L1/anti-CTLA-4 agents in mouse melanoma models." (PMID 34986841, 2022).
melanoma (continued). "Similarly, pan-HDAC inhibitors AR42 or sodium valproate enhanced the efficacy of both anti-CTLA-4 and anti-PD-L1 therapies in melanoma models." (PMID 35459932, 2022). "Similarly, CTLA-4 blockade with anti-CD25-mediated Treg depletion results in maximal rejection of B16-F10 melanoma tumors." (PMID 35326731, 2022). "In the past decade, the clinical management of patients with advanced melanoma was revolutionised by the use of anti-programmed cell death 1 (PD1) and/or anti-cytotoxic-T-lymphocyte-associated antigen 4 (CTLA-4) immunotherapies, as well as BRAF/MEK inhibiting targeted therapies." (PMID 34373567, 2022). "Remarkably, blocking CTLA‐4 in melanoma cells could also inhibit the particular competencies of melanoma stem‐like cells in vivo, comprising the capability for tumorigenesis." (PMID 35392976, 2022). "Among the 848 ICI-treated patients with advanced melanoma included in the study, 640 patients were treated with anti-PD-1 monotherapy (N = 251 stage 3, N = 389 stage 4) and 208 patients were treated with combination anti-CTLA-4/PD-1 therapy (all stage 4)." (PMID 36531890, 2022). "A study was conducted to identify factors associated with success or failure of checkpoint therapy, in which they performed transcriptomes analysis in immune cells from tumor samples of melanoma patients treated with checkpoint therapy (anti-PD-1, anti-CTLA4+PD-1, and anti-CTLA4)." (PMID 36679904, 2022). "This engineered antibody (a-CTLA4TGFβRIIecd and a-PDL1-TGFβRIIecd) significantly counteracted Tregs and restored beneficial TH1 cells in the TME, exhibiting superior antitumor efficacy than either the CTLA-4 antibody or PD-L1 antibodies in human melanoma (A375)–bearing NSG mice." (PMID 36189283, 2022). "Notably, IDO1 inhibitors have already entered clinical trials, combined first with chemotherapeutic drugs and then with immune check-point inhibitors, such as anti-CTLA-4 and/or PD-1, to turn melanoma tolerance into anti-melanoma immunity." (PMID 35408802, 2022). "Immune checkpoints that target the programmed cell death-1 (PD-1), programmed cell death ligand-1 (PD-L1), and cytotoxic T-lymphocyte-associated antigen-4 (CTLA-4) have received approval across a wide range of cancer types, including lung cancer, melanoma, and head and neck, among others." (PMID 35565373, 2022). "Unrivaled responses have been reported amongst advanced staged cancer patients, such as lung cancer, melanoma, bladder cancer, and Hodgkin’s disease, treated with anti-CTLA-4, PD-1/L1 therapies, although a minimal percentage of patients benefitted after such treatments." (PMID 35337133, 2022). "A higher real-life rate of cardiovascular events was assessed in a recent Danish registry in lung cancer or melanoma patients (1-year absolute risk of cardiac events of 9.7% and 6.6% with PD‐1 inhibitors, respectively, and melanoma 7.5% with CTLA‐4 inhibitors)." (PMID 35507087, 2022). "VSV∆51-amiR-4 combined with anti-CTLA4 treatment significantly (P value = 0.0013) enhanced tumour regression and prolonged overall survival of mice bearing subcutaneous (SC) B16-F10 melanoma tumours and was superior to anti-CTLA4 therapy when combined with VSV∆51 that lacks amiR-4." (PMID 35393414, 2022). "Furthermore, delayed administration of the JAK inhibitor after starting the anti-CTLA-4 Ab improved its antitumor response by decreasing expression of multiple immune checkpoint ligands on melanoma cells." (PMID 35432377, 2022). "Of the three stage IV melanoma patients who developed progress, one patient received additional immune checkpoint combination therapy with ipilimumab (anti-CTLA-4) and nivolumab (anti-PD-1) and developed a complete response until the end of the observation period (31 December 2021)." (PMID 36142629, 2022).
melanoma (continued). "Currently, PD-1 and CTLA-4 are the therapeutic targets against malignant melanoma, and anti-PD-1 antibody (nivolumab) and anti-CTLA-4 antibody (ipilimumab) are currently used as single-agent or combination therapies for advanced or recurrent cases, as well as adjuvant therapy after surgery." (PMID 35163049, 2022). "In a small case-series of three PWH on ART receiving anti-PD-L1 for Merkel cell carcinoma or combined anti-PD-1/anti-CTLA-4 for melanoma, we recently reported that ICB led to substantial increases in cell-associated HIV RNA of up to 16-fold relative to pre-treatment levels." (PMID 35123267, 2022). "Moreover, melanomas respond to immunotherapy with monoclonal antibodies that block the immune checkpoint receptors cytotoxic T-lymphocyte antigen 4 (CTLA4), such as ipilimumab, and programmed cell death protein 1 (PD1), such as pembrolizumab and nivolumab." (PMID 36500861, 2022). "Although immunotherapies targeting cytotoxic T lymphocyte antigen-4 (CTLA-4), programmed cell death protein-1 (PD-1), and programmed death-ligand 1 (PD-L1) can treat several solid malignancies such as melanomas, but they are ineffective for pancreatic cancer patients." (PMID 35719943, 2022). "In addition, recent reports have shown that systemic CD4+ T cells influence positively ICI outcomes and that a repertoire of pre-existing blood CD4+ T cells predicts better clinical outcomes in melanoma patients treated with anti-CTLA-4." (PMID 35008422, 2022). "The TIDE score predicts outcomes in melanoma patients who receive first-line anti-PD1 or anti-CTLA4 therapy by mimicking two escape mechanisms of tumors (T cell dysfunction signature and T cell exclusion signature) more accurately than other biomarkers, such as PD-L1 levels and mutation load." (PMID 36247009, 2022). "In addition, the immunosuppressive molecules CD200 and immune checkpoint proteins expressed on melanoma cells, such as CTLA-4 and PD-L1, have also been identified as immunotherapeutic candidates." (PMID 35401191, 2022). "Subsequently, they demonstrated that EZH2 inhibitor alone enhanced the cytotoxic activity of human CD8+ effector T cells, altered the phenotype and function of human Treg cells, and had an immunotherapy-sensitizing effect against CTLA-4 in mouse bladder cancer and melanoma models." (PMID 35140720, 2022). "High TMB was initially noted to correlate with response to anti-CTLA-4 immunotherapy in melanoma." (PMID 36389735, 2022). "AKI rates were significantly higher among patients with stage 4 melanoma (27.4% in patients treated with anti-CTLA-4/PD-1 combination therapy, 17.0% in patients treated with anti-PD-1 monotherapy), compared to 7.6% in patients with stage 3 melanoma receiving anti-PD-1 monotherapy." (PMID 36531890, 2022). "At present, antibodies targeting the cell surface programmed cell death 1 (PD-1) receptor (nivolumab or pembrolizumab), either in monotherapy or in combination with an antibody against the cytotoxic T-lymphocyte antigen-4 (CTLA-4) (ipilimumab), are the standard of care for melanoma patients." (PMID 36077430, 2022). "The one-year absolute risk of cardiac events after ICI initiation was 6.6% (95% CI: 1.8–11.3) in melanoma patients treated with PD-1 inhibitors, 7.5% (3.7–11.3) in melanoma patients treated with CTLA-4 inhibitors, and 9.7% in lung (95% CI: 6.8–12.5) cancer patients treated with PD-1 inhibitors." (PMID 35267453, 2022). "Higher mutational events in the tumor have been correlated with greater immunogenicity and survival after checkpoint blockade treatments, e.g., ipilimumab and tremelimumab are antibodies against cytotoxic T-lymphocyte antigen 4 (CTLA-4) treatment prolonged overall survival in patients with melanoma." (PMID 36679904, 2022). "Therefore, inhibiting tumor glycolysis in melanoma with high glycolytic flux is necessary to promote the anti-CTLA-4 effect." (PMID 36620597, 2022).
melanoma (continued). "Furthermore, we used subclass mapping analysis to contrast the expression profiles of the high-/low-score subgroups with a previously published dataset of 47 melanoma patients who accepted the immune checkpoint inhibitor therapy (CTLA-4 and PD-1)." (PMID 35309331, 2022). "CXCL12 gene expression signature predicts response to CTLA-4 checkpoint blockade in melanoma." (PMID 35552271, 2022). "Notably, neutralization of endogenous activin A by a soluble form of ActR-IIB sensitized melanoma grafts to combined anti-PD1/anti-CTLA4 blockade, supporting the clinical potential of targeting activin A to improve responses to immunotherapy in melanoma." (PMID 36353620, 2022). "A 4-monoclonal anti-CTLA inhibitor causes a pathological change mainly in melanoma-based sufferers, but there are several therapeutic NSCLC chemotherapy reports outlining the lymphocytes proliferated inappropriately following inhibition of CTLA-4." (PMID 35744922, 2022). "Notably, DNMT inhibitor treatment sensitizes tumors to anti-CTLA-4 therapy in a preclinical melanoma model, which is attributed to the re-activation of the interferon response pathway." (PMID 35693795, 2022). "Anti-CTLA-4 has been largely ineffective for the treatment of mouse melanoma as a monotherapy." (PMID 35651800, 2022). "Melanoma has been recognized as the most aggressive type of skin cancer and is particularly responsive to immunotherapy such as immune checkpoint blockade with CTLA4 and PD-1 antagonists." (PMID 36303162, 2022). "put forward the hypothesis that the optimal response in melanoma and other cancer types required radiotherapy together with the anti-CTLA-4 and anti-PD-L1/PD-1 antibodies." (PMID 35371055, 2022). "The combination of ipilimumab (IPI; anti–CTLA-4) and nivolumab (anti–PD-1) demonstrates superior response and survival in melanoma compared with single-agent nivolumab or IPI and, therefore, has become the preferred first-line regimen for many patients with advanced disease." (PMID 36173679, 2022). "Among the first-generation mAbs, the earliest CTLA-4 inhibitor ipilimumab and PD-1 inhibitor nivolumab/pembrolizumab have become first-line therapeutic options in advanced non-small cell lung cancer and melanoma cases." (PMID 33868786, 2021). "ICIs are approved for different indications, such as melanoma patients largely comprising the anti-CTLA-4 group, and the difference of approved indications may also account for the different risk shown in our study." (PMID 34276364, 2021). "Immune checkpoint blockade (ICB) targeting programmed cell death 1 (PD-1) and cytotoxic T-lymphocyte-associated antigen 4 (CTLA-4) has revolutionised the treatment of melanoma, with clinical benefit seen in up to 70% of patients when compared to either PD-1 (54%) or CTLA-4 blockade (41%) alone." (PMID 33918976, 2021). "In addition, prioritizing treatment with anti-PD1/L1 plus anti-CTLA-4 before MAPK inhibitor combination limits melanoma brain metastases." (PMID 34804979, 2021). "Hence, the use of anti-PD1 therapies (nivolumab and pembrolizumab) and anti-CTLA4 (ipilimumab) looks promising for the treatment of malignant melanoma in PLWH." (PMID 34831094, 2021). "We next analyzed the CPI1000+ data split by cancer/drug type, assessing four groupings where we had two or more independent cohorts available: melanoma anti-PD-1/L1, melanoma anti-CTLA-4, urothelial carcinoma anti-PD-1/L1, and non-small cell lung cancer anti-PD-1/L1." (PMID 33508232, 2021). "Moreover, we also found that the high expression levels of CXCL13, FCRLA, MS4A1, and PLA2G2D were positively associated with the better response of melanoma patients treated with anti-PD1 and anti-CTLA4." (PMID 34395521, 2021). "FNC‐producing MSNs loaded with CpG adjuvant and coated with a cancer cell membrane exhibited enhanced accumulation in lymph nodes and immune activation, and greater tumor growth inhibition alone and in combination with the immune checkpoint‐blocking antibody anti‐CTLA‐4 in a melanoma model." (PMID 34386315, 2021).